SFT2D1 (SFT2 domain containing 1)
Description:
May be involved in fusion of retrograde transport vesicles derived from an endocytic compartment with the Golgi complex.
Synonyms: C6orf83; MGC19825; pRGR1
Tractability: Antibody: UniProt predicts a signal peptide or a membrane-spanning region. PROTAC: ubiquitination databases record sites on it.
Gene: Protein-coding gene on chromosome 6 (166,319,724 to 166,342,590, reverse strand). Ensembl gene ENSG00000198818.
Subcellular location: Membrane
Subcellular location (Human Protein Atlas): Nuclear bodies; Cytosol; Nucleoplasm
Gene Ontology:
Molecular function: protein binding
Biological process: vesicle-mediated transport
Cellular component: cytoplasm; endomembrane system; membrane
Genetic constraint (gnomAD): Loss-of-function variants: 17 observed, 16.86 expected, observed/expected ratio (o/e) 1.01, 90% interval 0.69 to 1.51. The upper end of that interval is the gene's LOEUF score, 1.51, which puts it in group 6 of 6, group 1 being the genes least tolerant of losing a copy. Missense variants: 123 observed, 121.11 expected, observed/expected ratio (o/e) 1.02, 90% interval 0.88 to 1.18. Synonymous variants: 66 observed, 50.77 expected, observed/expected ratio (o/e) 1.3, 90% interval 1.07 to 1.6.
Homologues: Orthologues: chimpanzee SFT2D1 (99% identical), macaque SFT2D1 (97% identical), dog SFT2D1 (94% identical), guinea pig SFT2D1 (91% identical), mouse Sft2d1 (91% identical), mouse Sft2d1rt (91% identical), pig SFT2D1 (91% identical), rat Sft2d1 (81% identical), tropical clawed frog sft2d1 (77% identical), zebrafish sft2d1 (75% identical), rabbit SFT2D1 (74% identical), Drosophila melanogaster CG5104 (58% identical), and 1 more. Paralogues in human: SFT2D2 (64% identical), SFT2D3 (26% identical).
Diseases named in the same sentence as SFT2D1 in open-access papers:
SFT2D1 is named in the same sentence as 5 diseases in open-access papers, as found by Europe PMC text mining. Sharing a sentence is not in itself a finding about the gene and the disease. The quoted sentences say what the papers report.
cervical cancer (1 paper, 2024). A primary or metastatic malignant neoplasm involving the cervix. "GSEA pathway analysis results suggest that SFT2D1 plays an important role in tumor-related pathways and is associated with the invasion and progression of cervical cancer." (PMID 38200479, 2024). "Then we performed RT-qPCR to verify SFT2D1 was highly expressed in cervical cancer cell lines compared to normal cervical cell lines ECT1/E6E7." (PMID 38200479, 2024). "We verified SFT2D1 was significantly upregulated in cervical cancer cells by western blotting, RT-qPCR, and immunohistochemistry." (PMID 38200479, 2024). "Wound scratch assay showed that knockdown of SFT2D1 significantly inhibited the migration of cervical cancer cells." (PMID 38200479, 2024). "Knockdown of SFT2D1 significantly inhibited ability of the proliferation, migration, and invasive in cervical cancer cells." (PMID 38200479, 2024). "Finally, we verified an independent prognostic gene SFT2D1 was highly expressed in cervical cancer and positively correlated with the microvascular density." (PMID 38200479, 2024). "Therefore, SFT2D1, a CuRA modeling gene, may serve as a marker gene and provide a new reference for the treatment of cervical cancer patients." (PMID 38200479, 2024). "Meanwhile, we performed immunohistochemical analysis of SFT2D1 and the neovascularization marker CD31 in paraffin sections of cervical cancer patients." (PMID 38200479, 2024). "Since the role of SFT2D1 in cervical cancer has not yet been explored, we authenticated the effect of SFT2D1 on the function of SiHa and CaSki cells by in vitro experiments." (PMID 38200479, 2024). "The results showed both SFT2D1 and CD31 were expressed up-regulated in cervical cancer tissues." (PMID 38200479, 2024).
neuroblastoma (1 paper, 2024). Neuroblastoma (NB) is the most common solid, extracranial childhood tumor. "Among them, SFT2 Domain Containing 1 (SFT2D1) is involved in protein and vesicle-mediated translocation and is also associated with poor survival in patients with high-risk neuroblastoma." (PMID 38200479, 2024).
pancreatic cancers (1 paper, 2025). "For example, recent studies have linked SFT2D1 to tumor progression and immune modulation in cervical and pancreatic cancers, including associations with alternative splicing events and cellular transport pathways." (PMID 40370519, 2025). "Furthermore, alternative splicing events of SFT2D1 have been significantly associated with increased pancreatic cancer risk, suggesting a broader role in tumorigenesis." (PMID 40370519, 2025).
Sepsis (1 paper, 2025). Sepsis is defined as life-threatening organ dysfunction caused by a dysregulated host response to infection. "Third, while our study focused on sepsis, we note that these biomarkers, such as SFT2D1, have also been implicated in other disease contexts." (PMID 40370519, 2025). "Clinically, BLOC1S1, NDUFA1, and SFT2D1—have also been implicated in various disease contexts beyond sepsis." (PMID 40370519, 2025). "A scatter plot demonstrated a positive correlation between SFT2D1 expression and increased risk of sepsis." (PMID 40370519, 2025). "The IVW results indicated a causal link, identifying SFT2D1 as a risk factor for sepsis [odds ratio (OR) = 1.070, 95% confidence interval (CI) = 1.016–1.127, P = 0.001]." (PMID 40370519, 2025). "To assess the functional role of SFT2D1, which was identified as a genetic risk factor for sepsis through MR analysis, we conducted gene knockdown experiments in the LPS-induced THP-1 sepsis model." (PMID 40370519, 2025). "SFT2D1, though less studied, was confirmed as a risk factor for sepsis through MR analysis, highlighting its potential role in disease progression." (PMID 40370519, 2025). "Additionally, functional inhibition of SFT2D1 provides direct mechanistic insight into its role in sepsis-associated inflammation." (PMID 40370519, 2025). "Further analysis demonstrated that SFT2D1 inhibition significantly decreased the expression levels of key inflammatory cytokines CXCL10 and IL-6 (P < 0.05), suggesting a role for SFT2D1 in promoting the inflammatory response in sepsis." (PMID 40370519, 2025). "This study identified three histone acetylation-related genes, BLOC1S1, NDUFA1, and SFT2D1, as potential biomarkers for sepsis through integrated bioinformatics analysis." (PMID 40370519, 2025). "This study identified BLOC1S1, NDUFA1, and SFT2D1 as histone acetylation-related biomarkers for sepsis and validated their expression in THP-1 cell models and patient blood samples." (PMID 40370519, 2025). "Our experimental findings further demonstrated that SFT2D1 suppression mitigates pro-inflammatory cytokine expression, suggesting a functional role in sepsis pathogenesis." (PMID 40370519, 2025). "Importantly, our experimental results highlight the potential of SFT2D1 inhibition in reducing inflammatory responses, providing a new avenue for therapeutic development in sepsis management." (PMID 40370519, 2025). "In the present study, GSEA revealed that SFT2D1 may exert a crucial regulatory role in the inflammatory response of sepsis by activating the toll-like receptor signaling pathway." (PMID 40370519, 2025). "Moreover, SFT2D1 inhibition effectively attenuates inflammatory cytokine expression, highlighting its potential as a novel therapeutic target for sepsis management." (PMID 40370519, 2025). "Furthermore, validation using patient blood samples confirmed the elevated expression levels of BLOC1S1, NDUFA1, and SFT2D1 in sepsis patients compared to healthy controls." (PMID 40370519, 2025). "Additionally, the “toll-like receptor signaling pathway” was activated in BLOC1S1 and SFT2D1, which might indicate a key regulatory mechanism of the inflammatory response in sepsis." (PMID 40370519, 2025). "Furthermore, functional experiments demonstrated that suppression of SFT2D1 significantly reduced the expression of inflammatory cytokines CXCL10 and IL-6, suggesting its potential role in modulating the inflammatory response in sepsis." (PMID 40370519, 2025).
SFT2D1 also shares sentences with these, for which no sentence is quoted: tumor (3 papers).